ZBTB33 (zinc finger and BTB domain containing 33)
Description:
Transcriptional regulator with bimodal DNA-binding specificity. Binds to methylated CpG dinucleotides in the consensus sequence 5'-CGCG-3' and also binds to the non-methylated consensus sequence 5'-CTGCNA-3' also known as the consensus kaiso binding site (KBS). Recruits the N-CoR repressor complex to promote histone deacetylation and the formation of repressive chromatin structures in target gene promoters. May contribute to the repression of target genes of the Wnt signaling pathway. May also activate transcription of a subset of target genes by the recruitment of CTNND2. Represses expression of MMP7 in conjunction with transcriptional corepressors CBFA2T3, CBFA2T2 and RUNX1T1.
Synonyms: KAISO; ZNF348; ZNF-kaiso; WUGSC:H_DJ525N14.1
Tractability: Small molecule: a structure with a bound ligand is known. Antibody: its Gene Ontology location is reachable by antibodies, with high confidence; the Human Protein Atlas places it where antibodies can reach. PROTAC: UniProt records ubiquitination sites on it; ubiquitination databases record sites on it; its protein half-life has been measured.
Target class: Transcription factor
Gene: Protein-coding gene on chromosome X (120,250,752 to 120,259,741, forward strand). Ensembl gene ENSG00000177485.
Subcellular location: Nucleus; Cytoplasm
Subcellular location (Human Protein Atlas): Cytosol; Nucleoplasm; Plasma membrane
Pathways (Reactome):
Cell-Cell communication: Negative Regulation of CDH1 Gene Transcription
Gene Ontology:
Molecular function: methyl-CpG binding; protein binding; sequence-specific DNA binding; sequence-specific double-stranded DNA binding; DNA-binding transcription factor activity, RNA polymerase II-specific; DNA-binding transcription repressor activity, RNA polymerase II-specific; RNA polymerase II cis-regulatory region sequence-specific DNA binding
Biological process: negative regulation of DNA-templated transcription; intracellular signal transduction; negative regulation of transcription by RNA polymerase II; regulation of cytokine production; regulation of immune system process
Cellular component: cytosol; nucleoplasm; nucleus; plasma membrane; chromatin; cytoplasm
Homologues: Orthologues: chimpanzee ZBTB33 (99% identical), macaque ZBTB33 (99% identical), pig ZBTB33 (94% identical), dog ZBTB33 (93% identical), guinea pig ZBTB33 (92% identical), rabbit ZBTB33 (91% identical), mouse Zbtb33 (88% identical), rat Zbtb33 (87% identical), tropical clawed frog zbtb33 (56% identical), zebrafish zbtb33 (40% identical). Paralogues in human: ZBTB21 (21% identical), ZBTB46 (13% identical), NACC1 (13% identical), NACC2 (13% identical), ZBTB14 (13% identical), ZBTB49 (13% identical), BCL6 (12% identical), BCL6B (11% identical), ZBTB3 (10% identical), ZBTB12 (10% identical), ZBTB6 (10% identical), ZBTB26 (10% identical), and 16 more.
Diseases named in the same sentence as ZBTB33 in open-access papers:
ZBTB33 is named in the same sentence as 15 diseases in open-access papers, as found by Europe PMC text mining. Sharing a sentence is not in itself a finding about the gene and the disease. The quoted sentences say what the papers report.
breast carcinoma (5 papers, 2021 to 2024). "Other common upregulated transcription factor activity includes YBX1, associated with aggressiveness in breast cancer, and ZBTB33 (also known as Kaiso) which had been associated with metastatic activity in MDA-MB-231 cells." (PMID 38184712, 2024). "In breast cancer, ZBTB33 subcellular partitioning functionally linked LC3A/B, the tumor microenvironment, and cancer survival." (PMID 34858994, 2021).
glioma (5 papers, 2021 to 2024). A benign or malignant brain and spinal cord tumor that arises from glial cells (astrocytes, oligodendrocytes, ependymal cells). "Another study found that ZBTB33 is highly expressed in gliomas and tightly linked with proliferation, invasion, and EMT phenotype." (PMID 33459509, 2021).
prostate carcinoma (4 papers, 2020 to 2025). A carcinoma that arises from epithelial cells of the prostate gland. "ZBTB38 paralogs, ZBTB4 and ZBTB33/KAISO, are also implicated in the progression of prostate cancer." (PMID 32365491, 2020). "Shuttling of ZBTB33/KAISO into the nucleus in prostate cancer cells promotes cell invasion and migration; and in patients this phenomenon is correlated with more aggressive cancer parameters, including the ability to metastasise." (PMID 32365491, 2020).
colorectal cancer (2 papers, 2012 to 2023). A primary or metastatic malignant neoplasm that affects the colon or rectum. "A ZBTB family member that has recently been studied in detail for its ability to modulate colorectal cancer, Kaiso (ZBTB33), utilizes all three zinc fingers for high affinity binding to DNA targets." (PMID 23251453, 2012).
diabetes (2 papers, 2021 to 2022). "ZBTB33 is also found to be associated with diabetes mellitus and hepatocellular carcinoma." (PMID 33868403, 2021).
glioblastoma (1 paper, 2017). The most malignant astrocytic tumor (WHO grade IV). "Furthermore, the Tcf1 motif we identified in mESCs shares the same sequence of KAISO/ZBTB33 in adipocyte-specific promoters or DYRK1A in glioblastoma cell line." (PMID 28346462, 2017).
Obesity (1 paper, 2025). Accumulation of substantial excess body fat. "In addition, our analyses showed upregulation of a novel obesity gene (TBX15) and a gene recently found associated to hepatic inflammation and apoptosis in mice (ZBTB33)." (PMID 40489530, 2025).
systemic lupus erythematosus (1 paper, 2021). An autoimmune multi-organ disease typically associated with vasculopathy and autoantibody production. "ZBTB33 binds to a motif in the Ctse locus in a methylation-dependent manner, and subsequently represses the expression of Cathepsin E and IL-10 in murine thymoma EL-4 cells, and in CD4+ T cells of MRL/lpr mice or patients with systemic lupus erythematosus (SLE)." (PMID 34349770, 2021).
tumor (17 papers, 2017 to 2025). "Despite the diverse roles of ZBTB33 (KAISO) in cell-cycle progression, genome stability and tumor invasion, ZBTB33-deficient mice are grossly normal, and exhibit comparable composition and phenotype of peripheral leukocytes as control mice." (PMID 34349770, 2021). "AP-1 factors and STAT3 are particularly important for transformation in our model, and loss of ETS, KLF/SP1, THAP11, CREB, ZBTB33, or CEBP inhibits transformation or tumor growth in other cellular or animal models." (PMID 33523865, 2021). "SCENIC predicted the top 4 transcription factors that differed expressed most between the two subgroups of tumour cells: SAP30, UQCRB, ZBTB33 and ZNF165." (PMID 40830065, 2025). "The expression levels of three writers (DNMT1, DNMT3A, DNMT3B), two erasers (TET1, TET3), and eight readers (MBD4, ZBTB33, UHRF1, UHRF2, UNG, TDG, NTHL1, SMUG1) were dramatically higher in tumor tissues (p < 0.05)." (PMID 38317133, 2024). "Further investigation illustrated that DNMT1/3A/3B, TDG, SMUG1, UNG, NEIL1, MDB3/4, ZBTB33, and UHRF1/2 were essentially upregulated in tumor samples, while TET2, MBD1, and MBD2 were downregulated in tumor samples." (PMID 35205097, 2022). "Apart from SAR1B, ZBTB33, STYX, KLRC3, and S100Z, there were significant differences in the other 10 DEGs levels in the tumor-stroma crosstalk." (PMID 30519576, 2018). "It would thus be interesting to investigate whether a combination between expression levels of ZBTB4, ZBTB33/KAISO and ZBTB38 may help better categorised tumours with different molecular and clinical behaviour." (PMID 32365491, 2020). "Except for few being chromatin regulators (CGBP, MBD2, and DNMT1), all of these TFs were found to have tumor suppressor functionality (BRCA1, E2F1&2&5&7, EGR1-4, FLI1, NRF1, TFDP2, and STAT1), or indirectly mediate the suppression of tumorigenesis and tumor suppressor activity (SP4 and ZBTB33)." (PMID 29740534, 2018).
cancer (16 papers, 2016 to 2026). A tumor composed of atypical neoplastic, often pleomorphic cells that invade other tissues. "Most previous studies on ZBTB33 are related to cancer, but one study in mice related ZBTB33 to PGC-1a linked to hepatic inflammation and apoptosis, which indicates a potential role of ZBTB33 in NAFLD in humans and should be further investigated." (PMID 40489530, 2025). "By contrast, in cancer, ZBTB33 binding sites were highly mutated at positions 5 and 8, reflecting the high mutational input evident at ZBTB33 control motifs." (PMID 27490693, 2016). "ESRRA and XBP1 are known to regulate glucose, lipid, and mitochondrial metabolism while ZBTB33 is related to cell cycle progression and they have been found to be expressed in several types of cancer." (PMID 39217365, 2024). "Given the significance of ZBTB33/Kaiso function in the neurological processes and cancer, further investigation of the functional interaction between DCAF7, DYRK1A and Kaiso is justified." (PMID 37900285, 2023). "ZBTB33 (Kaiso) is a transcriptional repressor from the POZ-ZF family, with a context-dependent role in cancer." (PMID 41438580, 2026). "Third, ZBTB38 paralogs, ZBTB4 and ZBTB33, regulate the expression of CDKN1 family genes in cancer cells." (PMID 30310057, 2018).
ZBTB33 also shares sentences with these, for which no sentence is quoted: gastric cancer (1 paper); hepatocellular carcinoma (1); ischemic stroke (1); renal cell carcinoma (1); triple-negative breast carcinoma (1).